ANXA2 (annexin A2)
Diseases named in the same sentence as ANXA2 in open-access papers (continued):
Sharing a sentence is not in itself a finding about the gene and the disease.
cervical cancer (11 papers, 2009 to 2023). A primary or metastatic malignant neoplasm involving the cervix. "ANXA2 has also been identified as a “core protein” in cervical cancer, associated with tumor development and progression, as well as with response to chemotherapy." (PMID 31242951, 2019). "Concomitantly, the increase of ANXA2 expression was associated with a more aggressive phenotype among cervical cancer tissues examined in this study." (PMID 27402115, 2016). "The precise role of ANXA2 in cervical cancer is poorly understood, as indicated by conflicting reports on its protein expression." (PMID 37185759, 2023). "In the present study, levels of ANXA2 expression decreased in cervical cancer tissues compared to those in normal tissues; however, differences in subcellular localization were detected." (PMID 27402115, 2016). "In cervical carcinoma, three proteins were clearly upregulated compared with vaginal carcinoma and normal vaginal tissue (thiol-specific antioxidant prot, annexin A2 and alfa-2-actin)." (PMID 19367286, 2009). "Upregulation of annexin A2 (in line with our results) and A5 has been described in cervical carcinoma; however, annexin A1 was downregulated suggesting different roles for these annexins in the carcinogenesis of cervical squamous cell carcinoma." (PMID 19367286, 2009). "Only a few proteomic studies have been conducted in cervical carcinoma, for which proteins such as annexin A2, tropomyosin 1 and 2, peroxiredoxin 2 and HSP 27 have been pointed out as potential diagnostic markers." (PMID 19367286, 2009). "Nuclear ANXA2 was detected by Western blot in cervical cancer cell lines." (PMID 27402115, 2016). "ANXA2 was detected very strongly near the cytosolic membrane in normal cervical epithelial specimens, whereas it was detected in both membranes and the cytoplasm in cervical cancer tissues." (PMID 27402115, 2016). "Furthermore, we demonstrated that high ANXA2 and ANXA4 expression predicted poor survival in patients with cervical cancer, which was supported by the improved predictive power of a model using combined clinical-ANXA2/ANXA4-variables." (PMID 27402115, 2016). "Three proteins were uniquely altered in vaginal carcinoma (DDX48, erbB3-binding protein and biliverdin reductase) and five in cervical carcinoma (peroxiredoxin 2, annexin A2, sarcomeric tropomyosin kappa, human ribonuclease inhibitor and prolyl-4-hydrolase beta)." (PMID 19367286, 2009). "However, three proteins were significantly altered in vaginal cancer exclusively (DEAD box, erbB3-binding protein and biliverdin reductase), and six proteins in cervical cancer (peroxiredoxin 2, annexin A2, sarcomeric tropomyosin kappa, Rnas inhib chain A and prolyl-4-hydrolase beta)." (PMID 19367286, 2009). "Some of the most promising cervicovaginal fluid-based biomarkers for cervical cancer found until now are ACTN4, VTN, ANXA1, ANXA2, CAP1, and MUC5B." (PMID 35645371, 2022). "In conclusion, our results show that ANXA2 and ANXA4 protein expression, alone or in combination, are independently poor prognostic factors of survival in patients with cervical cancer." (PMID 27402115, 2016). "Multivariate analysis indicated that ANXA2+ (HR = 2.72, p = 0.003) and ANXA2+/ANXA4+ (HR = 2.69, p = 0.039) are independent prognostic factors of disease-free survival in cervical cancer." (PMID 27402115, 2016). "In the present study, we investigated the prognostic significance of ANXA2 and ANXA4 in cervical cancers using immunohistochemistry and quantitative image analyses." (PMID 27402115, 2016). "The positive correlation between mRNA and protein expression was more prominent in squamous cell carcinoma for ANXA2 and in adenocarcinoma for ANXA4, suggesting that these ANXs potentially have different roles according to cervical cancer cell type." (PMID 27402115, 2016). "The present study was to investigate the clinical significance of annexin A2 (ANXA2) and annexin A4 (ANXA4) expression in cervical cancer." (PMID 27402115, 2016).
cervical cancer (continued). "Therefore, due to the historical relationship between HSV and cervical cancer, the down regulation of an inhibitory ligand of annexin A2 by HSV, and annexin A2’s implication in different viral entry pathways such as HIV, we hypothesized that the infection of HPV16 is also mediated through A2t." (PMID 22927980, 2012). "Although annexin A2 and cornulin have been reported in other studies, their expression in cervical cancer FFPE tissues has not been reported." (PMID 37185759, 2023). "To investigate a putative role of ANXA2, NDRG1 and STAT1 on radiation/drug-mediated killing of tumor cells, we set up in vitro experiments using radiosensitive (C-4I) or radioresistant (CaSki) cervical cancer cells." (PMID 31242951, 2019). "We also found that ANXA2 and ANXA4 were differentially expressed according to cell type, suggesting that each ANX potentially has a different role in squamous cell carcinoma or adenocarcinoma in patients with cervical cancer." (PMID 27402115, 2016). "However, knowledge on the clinical and prognostic significance of ANXA2 and ANXA4 expression in patients with cervical cancer is limited." (PMID 27402115, 2016). "ANXA2 and ANXA4 immunohistochemical staining were performed on a cervical cancer tissue microarray consisting of 46 normal cervical epithelium samples and 336 cervical cancer cases and compared the data with clinicopathological variables, including the survival of cervical cancer patients." (PMID 27402115, 2016).
non-small cell lung carcinoma (11 papers, 2017 to 2025). A group of at least three distinct histological types of lung cancer, including non-small cell squamous cell carcinoma, adenocarcinoma, and large cell carcinoma. "In our previous studies, we found that Annexin A2 is up-regulated in the cisplatin-resistant non-small cell lung cancer cell line A549/DDP." (PMID 28886730, 2017). "in non-small cell lung cancer demonstrated that CAFs promote ANXA2 expression and phosphorylation via secretion of hepatocyte growth factor (HGF) and insulin-like growth factor 1 (IGF-1), activating c-MET and IGF-1R receptors, thereby enhancing the epithelial–mesenchymal transition (EMT) process." (PMID 40837013, 2025). "In addition, ANXA2 was found to promote mitochondrial membrane fusion by regulating optic atrophy 1 (OPA1) expression in non-small cell lung cancer, thereby enhancing mitochondrial metabolic adaptation and preventing apoptosis." (PMID 40234383, 2025). "Similarly, in previous study, non-small cell lung cancer cell lines with ANXA2 silencing showed inhibition both in tumor growth and cell proliferation and also induced cell cycle arrest at the G2 phase." (PMID 31186633, 2019). "In non-small cell lung cancer (NSCLC), tumour-derived ANXA2 activates Toll-like receptor 2 (TLR2) receptors and downstream signalling on tumour-associated neutrophils (TANs), subsequently promoting ARG1 expression." (PMID 40234383, 2025).
Obesity (11 papers, 2018 to 2025). Accumulation of substantial excess body fat. "The increased levels of specific ITGA5, LITAF, TIMP1 and ANXA2 mRNA isoforms in HIGH pigs is consistent with reports indicating that the overexpression of these four genes is associated with obesity and metabolic disorders in humans." (PMID 29444639, 2018). "Previous studies have demonstrated that Anxa2 silencing alleviates the progression of acute pancreatitis, obesity-induced insulin resistance, and pediatric neuroblastoma by inhibiting the NF-κB signaling pathway." (PMID 38253182, 2024). "Applicable for obesity and the metabolic syndrome, AnxA2 depletion attenuated obesity-induced insulin resistance through suppression of NFκB signaling." (PMID 33810523, 2021). "Diet-induced obesity led to elevated AnxA2 protein levels in both fat depots, which was also increased in the liver and skeletal muscle." (PMID 31337068, 2019). "The upregulation of certain mRNA isoforms of the ITGA5, TIMP1, ANXA2 and LITAF genes in HIGH pigs is relevant because these four genes have been implicated in human obesity and diabetes." (PMID 29444639, 2018). "Likewise, discordant findings were also published on the regulation of AnxA2 expression in murine obesity." (PMID 31337068, 2019). "Thirty of 38 combinations were related to obesity indicators, and 5 proteins (annexin II [Annexin A2], coagulation FXI, Kininostatin-1, LRP12, and prekallikrein [plasma kallikrein]) showed consistent mediation effects on the associations of 3 obesity indicators with VTE risk." (PMID 38029854, 2024). "Accordingly, we found that genes related to angiogenesis (e.g., ANGPT1, ANXA2), as well as to TGFβ signaling (e.g., SMAD4, BMPER, AKT2) are modulated in obesity condition." (PMID 30838002, 2019). "Anxa2−/− mice exhibited defective fatty acid uptake by the WAT endothelium and adipocytes, making this regulatory circuit a new target for metabolic intervention in obesity." (PMID 33810523, 2021).
esophageal cancer (9 papers, 2012 to 2024). A primary or metastatic malignant neoplasm involving the esophagus. "Contrary to most organs of the DS, in esophageal cancers ANXA2 seems to be downregulated in most cases." (PMID 39594718, 2024). "ANXA2 is reported to be overexpressed in esophageal cancer and is involved in cancer progression by activating the MYC-HIF1A-VEGF axis." (PMID 35646067, 2022). "Furthermore, the loss of E3 ubiquitin ligase FBXW7 function has also been shown to lead to an increase in ANXA2 expression levels, thus promoting the malignant progression of esophageal cancer through ERK activation." (PMID 38658569, 2024). "ANXA2 promoted esophageal cancer progression by activating MYC-HIF-1α-VEGF axis." (PMID 38429756, 2024). "However, further studies on the regulatory mechanisms of ANXA2 and specific biological processes involved in esophageal cancer are still required." (PMID 38658569, 2024). "Regrettably, there have been few studies on ANXA2 in esophageal cancer." (PMID 38658569, 2024). "Furthermore, in esophageal cancer, ANXA2 expression was overexpressed and promoted the tumor progression by activating the MYC/HIF1A/VEGF signaling pathway." (PMID 35977942, 2022). "However, the mechanism of ANXA2 in esophageal cancer is not fully understood." (PMID 38658569, 2024). "Co-expression of ANXA2 with HOXA13 and SOD2 has also been found to play a prognostic role in esophageal cancer." (PMID 38658569, 2024). "In esophageal cancer, the role of ANXA2 is not yet well studied, with research coming up with seemingly contradictory findings." (PMID 39594718, 2024).
leukemia (9 papers, 2015 to 2024). A malignant (clonal) hematologic disorder, involving hematopoietic stem cells and characterized by the presence of primitive or atypical myeloid or lymphoid cells in the bone marrow and the blood. "In PML-RARα-associated APML expression of the ANXA2/S100A10 complex causes hyperfibrinolysis due to the accumulation of plasmin on the surface of leukemia cells." (PMID 39567540, 2024). "High expression of S100A10 is essential for ANXA2 phosphorylation mediated by Src kinase in leukemia." (PMID 33324631, 2020). "In leukemia, a role for ANXA2 has only been reported on tumor cells." (PMID 39567540, 2024). "Furthermore, it has been proposed that circ-ANXA2 enhances the expression of its parental gene, ANXA2, which stimulates fibrinolysis and matrix invasion of leukemia cells and induce chemo refractoriness." (PMID 37124518, 2023). "A single gene may be involved in different diseases; for example, ANXA2 is involved in carcinoma, osteoporosis, and leukemia." (PMID 27878450, 2017). "We then hypothesized that there is differential oncogene- and/or lineage-dependent sensitivity of leukemias to mTORC2 signaling downstream of the IGF1R, which may explain the observed phenotypes of CML, B-ALL and AML in ANXA2 KO mice." (PMID 39567540, 2024). "Treatment with small molecules that inhibit the S100A10–annexin A2 interaction, antibodies against annexin A2 and S100A10, or the knockdown of S100A10 could all increase the sensitivity of NTPL-20 leukemia cells to the chemotherapy drug vincristine." (PMID 30572596, 2018).
lung adenocarcinoma (9 papers, 2014 to 2025). A carcinoma that arises from the lung and is characterized by the presence of malignant glandular epithelial cells. "The pivotal role of the MUC5AC/ANXA2 signaling axis in facilitating brain metastasis from lung adenocarcinoma underscores its significance in cancer progression." (PMID 40655139, 2025). "It is interesting to note that the lncRNA MIR99AHG could promote autophagy by binding to ANXA2, then generate miR-99a to suppress the expression of mTOR, postponing lung adenocarcinoma progression." (PMID 35158722, 2022). "In summary, the MUC5AC/ANXA2 signaling pathway, modulated by CCL22, exerts a profound influence on the development of brain metastases from lung adenocarcinoma." (PMID 40655139, 2025). "The expression of ANXA2 in breast invasive carcinoma (BRCA), KICH, lung adenocarcinoma (LUAD) and PRAD was lower compared with corresponding normal tissues." (PMID 36713082, 2023). "Intense ANXA2 immunoreactivity is detected in lung adenocarcinoma and squamous cell carcinoma, compared to noncancerous control." (PMID 24591759, 2014).
multiple myeloma (9 papers, 2014 to 2024). "Higher AnxA2 expression in myeloma cells is associated with significantly more adverse prognostic features, and inferior event-free and overall survival." (PMID 35328533, 2022). "Preclinical studies show that AnxA2 is highly expressed in myeloma cells from MM patients and can promote myeloma cell growth, reduce apoptosis in myeloma cell lines, and increase osteoclast formation." (PMID 35328533, 2022). "Recently, it has been demonstrated that annexin A2, expressed on stromal cells, regulated bone marrow homing of Multiple Myeloma cells supporting their growth and regulating their adhesion to stromal cells." (PMID 27196940, 2016). "ANXA2 silencing inhibits cell division and proliferation following the blockade of DNA synthesis in the cervical cancer cell line HeLa as well as the multiple myeloma cell lines U266 and RPMI8226." (PMID 24591759, 2014). "Myeloma cells from MM patients display an increased expression of ANXA2 compared to plasma cells from normal subjects." (PMID 24591759, 2014). "ANXA2, on the other hand, facilitates the homing of multiple myeloma cells to the BM6." (PMID 39567540, 2024). "Furthermore, it has been recently demonstrated that annexin A2, expressed on stromal cells, regulates bone marrow homing of Multiple Myeloma cells supporting their growth, through the activation of ERK 1⁄2 and AKT, and regulating their adhesion to stromal cells." (PMID 27196940, 2016). "Thus, ANXA2 levels, which are easily measured in serum, could be a clinical prognostic factor for multiple myeloma." (PMID 24591759, 2014).
oral squamous cell carcinoma (9 papers, 2014 to 2024). "Annexin A2 protein may play an important role in carcinogenesis of oral squamous cell carcinoma (OSCC)." (PMID 24884814, 2014). "However, a prognostic significance in cancer has been suggested for IFITs and a novel role for IFIT1 and IFIT3 has been suggested in progression and metastasis in oral squamous cell carcinoma through interaction with annexin A2, which enhances recycling of the EGF receptor." (PMID 38447798, 2024). "In oral squamous cell carcinoma (OSCC), there is an elevated ANXA2 mRNA and protein expression in cancerous HB56 and HB96 cells over human immortalized oral epithelial cells." (PMID 24591759, 2014).
rheumatoid arthritis (9 papers, 2005 to 2026). A chronic, systemic autoimmune disorder characterized by inflammation in the synovial membranes and articular surfaces. "Indeed, high levels of ANXA2 have been measured in several immune-mediated diseases and in synovial tissues of patients with rheumatoid arthritis and osteoarthritis, causing cartilage destruction by promoting migration and invasion of fibroblast-like synoviocytes into cartilage." (PMID 32466468, 2020). "Even though ANXA2 is considered a pro-inflammatory factor in autoimmune diseases such as rheumatoid arthritis, in supplemented horses, its increased expression could facilitate the migration of immunocompetent cells through tissues." (PMID 36983904, 2023). "In Rheumatoid Arthritis (RA), AnxA2 is significantly higher in plasma, synovial fluid, and synovial tissues, acting as an upstream regulator of cytokines and chemokines driving RA pathogenesis." (PMID 41550928, 2025). "In this study, we discovered that ANXA2 knockdown results in upregulation of DEGs that were abundant in various pathways such as ECM-receptor interaction, lysosome, rheumatoid arthritis, phagosome, and PI3K-AKT signaling pathway." (PMID 36159852, 2022).
diabetes (8 papers, 2008 to 2025). "Nevertheless, the underlying mechanism through which Anxa2 regulated EGFR signaling in diabetes‐related CIRI remains elusive." (PMID 39912333, 2025). "In our included patients, single‐factor logistic regression analysis identified ANXA2, male sex, diabetes mellitus, smoking, blood creatinine, and leukocytes as risk factors for developing coronary heart disease." (PMID 36932468, 2023). "After adjustment for confounders, multivariable logistic regression analysis found that ANXA2, male sex, diabetes, leukocytes, and blood creatinine were independent risk factors for CAD." (PMID 36932468, 2023). "High glucose (diabetes) is typically associated with a low-fibrinolysis state, which seems contradictory to our present finding of up-regulated Annexin A2 in the GDM placenta villi." (PMID 22970290, 2012). "Hence, these findings clearly indicated that the lncRNA‐MEG3 inhibition‐exerted protective effects probably involved phosphorylated activation and mitochondrial translocation of Anxa2 in diabetics during CIRI progression." (PMID 39912333, 2025). "Previous studies showed that Annexin A2 is up-regulated on the surface of endothelial cells by high concentrations of glucose and acts as an intermediate in diabetes-induced enhancement of plasmin activity in the aorta; and thus counteracts the hyper-thrombotic trend in vessels of diabetic patients." (PMID 22970290, 2012). "Furthermore, Anxa2, serving as a lncRNA‐MEG3‐associated mitochondrial protein, was found to be essential for the protective role of lncRNA‐MEG3 inhibition against neuronal mitochondria‐related apoptosis in diabetes combined with the CIRI model." (PMID 39912333, 2025). "Although dysregulation of ANXA1 and ANXA2 has been documented in diabetes, changes in ANXA3 have not been reported." (PMID 37895816, 2023).